FOXP3 (forkhead box P3)
Diseases named in the same sentence as FOXP3 in open-access papers (continued):
Sharing a sentence is not in itself a finding about the gene and the disease.
non-small cell lung carcinoma (65 papers, 2011 to 2025). A group of at least three distinct histological types of lung cancer, including non-small cell squamous cell carcinoma, adenocarcinoma, and large cell carcinoma. "In other cancers, B7-H3 high expression has been shown to be positively associated with the immunosuppressive FOXP3+ regulatory T cells in renal cell carcinoma and non-small cell lung cancer." (PMID 38612786, 2024). "In contrast, tumor FOXP3 has been identified as a biomarker associated with malignant prognosis in pancreatic cancer, non-small cell lung cancer (NSCLC), thyroid cancer, and melanoma." (PMID 37868998, 2023). "The expression of FOXP3 has been reported to be associated with poor prognosis in some tumors, and FOXP3 can promote tumor growth in non-small cell lung cancer." (PMID 36466923, 2022). "For instance, Foxp3+ TILs were reported to be linked to favourable clinical outcomes in non-small cell lung cancer (NSCLC) and sinonasal squamous cell carcinoma, but others reported that Foxp3+ TILs were correlated with to worse prognosis." (PMID 32758195, 2020). "For example, in non-small cell lung cancer, high expression of FoxP3 was associated with smoking." (PMID 37345025, 2023). "Together, these results demonstrate that FOXP3 has broad functions as a tumor suppressor in breast and prostate cancers and a tumor promoter in non-small cell lung cancer, suggesting that the regulatory machinery associating with FOXP3 in each cancer type might be critical for FOXP3 function." (PMID 34768829, 2021). "In non-small cell lung cancer, FOXP3 activated the downstream Wnt pathway through the interaction of β-catenin and TCF4, promoting tumor proliferation and metastasis." (PMID 39668835, 2024). "Previously, we mentioned that FoxP3 has been shown to promote the EMT pathway in non-small cell lung cancer." (PMID 37569676, 2023). "The EMT phenotype is positively correlated with PD-L1, PD-L2, PD-1, TIM-3, B7-H3, BTLA, and CTLA-4 expression, as well as CD4+ Foxp3+ Tregs expansion in non-small cell lung cancer (NSCLC)." (PMID 37152039, 2023). "For example, high-level FOXP3 contributes to the proliferation and metastasis of non-small cell lung cancer cells." (PMID 35401877, 2022). "We examine the expression of YTHDF1, YTHDF2, CD8, CD4, and FOXP3 to identify their prognostic or predictive role for PD-1/PD-L1 inhibitor in non-small cell lung cancer (NSCLC)." (PMID 36479088, 2022). "FOXP3 can activate the Wnt/beta-catenin signaling pathway, thus, inducing epithelial–mesenchymal transition and promoting the progression of non-small cell lung cancer." (PMID 34901000, 2021). "In non-small cell lung cancer, SUVmax was correlated with CD8(+) TILs as well as CD163(+) tumor-associated macrophages, FoxP3(+) Treg cells, and PD-1(+) and PD-L1(+) cells." (PMID 34103577, 2021). "Previous studies on non-small cell lung cancer and Pancreatic Adenocarcinoma (PAAD) have shown the association of Forkhead box P3 (FOXP3) expression (marker of Tregs) with poor survival." (PMID 35096592, 2021). "For instance, overexpressed Foxp3 in non-small cell lung cancer can act as a co-activator to facilitate the Wnt/β-catenin signaling pathway, leading to the induction of EMT and the stimulation of tumor growth and metastasis." (PMID 31690033, 2019). "We aimed to study FOXP3 expression and regulation, function and clinical implication in human non-small cell lung cancer (NSCLC)." (PMID 28716029, 2017). "Gemcitabine combined with cisplatin chemotherapy significantly reduce the population of CD4 + CD25 + FOXP3+ Treg in patients with non-small cell lung cancer." (PMID 27435207, 2016). "In non-small cell lung cancer, FoxP3 could promote tumor metastasis through the Wnt/β-catenin signaling pathway and EMT." (PMID 37569676, 2023). "FOXP3 was reported to promote tumor growth and metastasis by activating the Wnt/β-catenin signaling pathway, according to previous research studies on non-small cell lung cancer." (PMID 36704358, 2022).
non-small cell lung carcinoma (continued). "However, FOXP3 has been shown to promote cancer growth and metastasis in non-small cell lung cancer." (PMID 34768829, 2021). "A similar study in non-small cell lung cancer also showed a better response rate to platinum-based ICT in patients with higher CD8+/FOXP3+ ratios (both in adenocarcinomas and squamous cell carcinomas), although CD8+ TIL infiltration was only associated with the response to ICT in adenocarcinomas." (PMID 33923066, 2021). "FOXP3 overexpression of Tregs may promote tumor cell growth in non-small cell lung cancer (NSCLC) microenvironment." (PMID 31815635, 2019). "However, decreased Treg frequencies and FOXP3 expression upon treatment with HDAC6-selective inhibitors have also been demonstrated in models of non-small cell lung cancer and multiple myeloma." (PMID 30728070, 2019). "Moreover, a previous study showed that in non-small-cell lung cancer, demethylation of the FOXP3 gene promoter could reduce the activity of DNMTs in Tregs CD4+ lymphocytes and downregulate immune responses in the TME." (PMID 35517856, 2022). "For example, SNORA38B promotes IL-10 secretion in tumor cells, leading to the recruitment of CD4+FOXP3+regulatory T cells and reduced infiltration of CD3+CD8+T cells in the TME of non-small cell lung cancer (NSCLC), thereby promoting tumor progression." (PMID 41019058, 2025). "A prospective study involving 89 early-stage non-small cell lung cancer patients demonstrated that SBRT increased CD4+ and CD8+ T-cell levels and significantly changed transcription factors such as TBX21, GATA-3, and FOXP3." (PMID 40283008, 2025). "We found that the accumulation of Foxp3+Treg cells in lung cancer is higher than that in normal tissues, and the increased infiltration of regulatory T cells into the core tumor area may be an independent predictor of poor overall survival in non-small cell lung cancer (NSCLC) patients." (PMID 38919615, 2024). "In order to determine if CCR8+ FOXP3− Tconv cells are enriched in human tumors, we analyzed CD4+ T cells from 48 patents with non-small cell lung carcinoma (NSCLC) by flow cytometry." (PMID 38100544, 2023). "Furthermore, as previously discussed, SNORA38B promotes the secretion of IL-10 by tumor cells, which recruit CD4+FOXP3+ regulatory T cells and reduce CD3+CD8+T cell infiltration in the TME of non-small-cell lung cancer." (PMID 41019058, 2025). "Similarly, DC-based high hydrostatic pressure (HHP) lung cancer vaccine decreased the number of CD4+CD25+Foxp3+ Tregs and Increased IFN-γ-producing tumor antigen-specific CD4+ and CD8+ T cells from non-small cell lung cancer (NSCLC) patients." (PMID 40050933, 2025). "A series of 98 tissue samples of primary non-small-cell lung carcinomas (NSCLC) from patients treated with surgery were analysed for the expression of CA9 and programmed-death ligand PD-L1 by cancer cells, and of FOXP3 by tumour-infiltrating lymphocytes (TILs)." (PMID 32066909, 2020). "However, the Helios+ subpopulation among CD4+Foxp3+ T cells in peripheral blood did not significantly differ between non-small-cell lung cancer (NSCLC) patients and healthy donors." (PMID 34257746, 2021).
prostate carcinoma (64 papers, 2010 to 2025). A carcinoma that arises from epithelial cells of the prostate gland. "FOXP3 is frequently downregulated or inactivated by a mutation(s) in prostate cancer, and reactivation of FOXP3 expression suppresses cancer growth." (PMID 30863497, 2019). "Overall, these results demonstrate that FOXP3 is a novel X-linked tumor suppressor and transcriptional repressor for breast and prostate cancers, suggesting a unique therapeutic opportunity for cancer treatment." (PMID 30011797, 2018). "According to these authors, mutations in FOXP3 occur exclusively in some types of tumors, such as breast and prostate cancer." (PMID 28603524, 2017). "In our previous studies, we demonstrated that, in breast and prostate cancers, FOXP3 is an X-linked tumor suppressor gene." (PMID 28562349, 2017). "Further, they also showed that inactivating deletions or point mutations are fairly common in the FOXP3 gene in human prostate cancers and PIN lesions, and that FOXP3 can directly repress MYC mRNA levels." (PMID 20195545, 2010). "In addition, recent work has implicated infiltrating TH17 and/or Treg (FoxP3+) T-cells in development or progression of human prostate cancer." (PMID 21394210, 2011). "However, prostate cancer TIL populations are mainly composed of CD4+FOXP3+CD25+ Treg cells and M2-type tumor-associated macrophage (TAM) cells, which contribute to the production of inhibitory cytokines and the maintenance of self-tolerance to suppress the immune response." (PMID 35892678, 2022). "Indeed, a prostate cancer susceptibility locus (loci) has been mapped on Xp11.2 associated with the SNP rs5945572, adjacent of which multiple tumor suppressor genes, including FOXP3 and AMER1 (also known as WTX and FAM123B), are located." (PMID 30863497, 2019). "Also, in a study concerning FOXP3 expression in prostate cancer cells, the authors demonstrated that genetic mutations in this gene could be detected in cancer cells and restrained its expression in the cytoplasm." (PMID 24877082, 2014). "Diverse PD-1, CD163, and FOXP3 profiles were observed in primary and metastatic microenvironments of prostate cancer." (PMID 41179298, 2025). "Our objective was to assess the prognostic significance of T (CD3+), T regulatory (Treg) (FoxP3+) and T memory (Tmem) (CD45RO+) infiltrating lymphocytes and of genes associated with TIL in prostate cancer (PCa)." (PMID 38887294, 2024). "Single-cell analysis revealed that CD4+ FOXP3+ CD25+ T cells and CD8+ FOXP3+ CD25+ T cells are the main T-cell types in prostate cancer." (PMID 37546397, 2023). "Based on the median number, we classified each prostate cancer case as having a high or low density of Foxp3+ Tregs." (PMID 35131860, 2022). "Surprisingly, we found that the TILTregSig represented high potential as an indicator of Tregs (AUC = 0.897), as compared to FoxP3 being a predictor with moderate potential in prostate cancer (AUC = 0.763)." (PMID 35812443, 2022). "High mRNA expression of CCL17, CCL22, CCR4, and Foxp3 was detected in 5.0%, 3.0%, 2.2%, and 5.0% of patients with prostate cancer, respectively." (PMID 35131860, 2022). "In prostate cancer, Foxp3 repress the transcription of c-MYC leading to inhibition of cell cycle progression and apoptosis." (PMID 35326661, 2022). "Specifically, prostate cancer patients with low CD8 +/strong PRSS2 expression or high FoxP3 +/strong PRSS2 expression had significantly poorer outcome." (PMID 36575174, 2022). "We searched for mRNA expression of CCL17, CCL22, CCR4, and Foxp3 in the publicly available transcriptomic dataset of human prostate cancer from TCGA PanCancer Atlas (n=493)." (PMID 35131860, 2022). "More tumor-infiltrating CCR4+ cells were evident in dogs with prostate cancer, the density being positively correlated with the number of Foxp3+ Tregs." (PMID 35131860, 2022).
prostate carcinoma (continued). "Only a few Foxp3+ Tregs were detected in the normal canine prostate, whereas they were observed both within the tumor and in the surrounding stroma in canine prostate cancer." (PMID 35131860, 2022). "FoxP3-expressing CD8+ Tregs have previously been reported to effectively suppress naïve T cell proliferation in prostate cancer." (PMID 35804964, 2022). "Analysis of a transcriptomic dataset of human prostate cancer showed that the CCL17–CCR4 axis correlated with Foxp3." (PMID 35131860, 2022). "At the cellular level, the T cell population in prostate cancer largely consists of CD4+ FOXP3+ CD25+ T cells and CD8+ FOXP3+ CD25+ T cells." (PMID 34063238, 2021). "Extensive studies in the past 20 years have strongly suggested that FOXP3 is a novel tumor suppressor, especially in breast, colon, and prostate cancers." (PMID 34768829, 2021). "This was reported to be the case in breast and prostate cancer in particular, where FOXP3 expression was found in normal epithelial cells and its downregulation was related to cancer development." (PMID 34484217, 2021). "Knocking-down of FOXP3 results in an elevated MYC expression in human prostate epithelial cells (HPECs), and reactivation of FOXP3 expression downregulates MYC expression in prostate cancer cell lines." (PMID 30863497, 2019). "Results show an increased number of tumor-infiltrating lymphocytes, including potentially immunosuppressive FOXP3-positive lymphocytes, in BRCA2-mutated prostate cancers compared to the BRCA1/2 wild-type group, which harbored mostly extratumoral immune cells." (PMID 31549213, 2019). "Thirdly, the FOXP3-miR-146-NF-κB axis has a functional role during tumor initiation in both breast and prostate cancers." (PMID 30011797, 2018). "Recent extensive studies have strongly suggested that FOXP3 is a novel tumor suppressor in breast and prostate cancers." (PMID 30011797, 2018). "We show that activated Wnt signalling is correlated with immune suppression in primary PC, and suggest that activated Wnt/β-catenin, MMR, high INIF and the CD8+/FOXP3+ ratio should be explored as predictive biomarkers for immunotherapeutics in prostate cancer." (PMID 28961847, 2017). "Foxp3 protein can be found in the majority of epithelial nuclei of the normal prostate and in about 30% of prostate cancer tissue samples, where served as a tumor suppressor via transcriptionally repressing cMYC gene." (PMID 27557492, 2016). "In prostate cancer cells, it was also validated that FOXP3 transcriptionally inhibits IRAK1 and TRAF6 through an induced expression of miR-146a/b." (PMID 26682271, 2015). "The functional FOXP3-miR-146-NF-κB axis during tumor initiation in prostate cancer cells was identified in prostate Foxp3 conditional knockout (Foxp3cKO) mice." (PMID 26682271, 2015). "Increased levels of Tregs, or increased expression of Foxp3 and enhanced Tregs function have been reported in cancer patients, including kidney and prostate cancer patients." (PMID 22303460, 2012). "Foxp3 was detected in epithelial cells of breast and prostate cancer patients, speculating that inhibition of Foxp3 expression in epithelial tumor cells may be a mechanism for tumors to escape immune surveillance." (PMID 37342563, 2023). "Entinostat, a histone deacetylase inhibitor, inhibits the proliferation and growth of Treg populations by activating STAT3 acetylation and reducing FoxP3 expression, suggesting a novel and effective approach to modulate the immune system and treat prostate cancer." (PMID 35892678, 2022).
prostate carcinoma (continued). "Studies have shown that PTEN deficiency is associated with the immunosuppressive state of prostate cancer, including lower CD8+ T cell and higher FoxP3+ Treg cell abundance, while the lower abundance of M2 macrophages was found in PTEN-deficient metastatic lymph nodes." (PMID 35892678, 2022). "Finally, loss of FOXP3 and TSC1 accelerates prostate cancer progression through synergistic regulation of c-MYC." (PMID 34768829, 2021). "Inactivation and/or mutations of TSPX and/or FOXP3 tumor suppressors at the Xp11.2 locus might impair their regulatory functions on MYC expression, thereby exacerbating the susceptibility of prostate cancer initiation and progression." (PMID 30863497, 2019). "In addition, immunosuppressive cells such as FOXP3-positive regulatory T cells and CD163-positive tumor-associated (M2) macrophages were also found to be enriched in prostate cancer and associated with a more unfavorable patient outcome." (PMID 31549213, 2019). "Similarly, two studies identified a CD8+FoxP3+ subset of TREG in patients with colorectal and prostate cancer, suggesting that FoxP3 can be expressed in CD8+ T cells and promote an immunosuppressive phenotype in cancer patients." (PMID 27314056, 2016). "Additionally, the identification of the FOXP3-miR-146-NF-κB axis provides a mechanism for NF-κB activation as well as miR-146a/b disruption in breast and prostate cancer cells, allowing for a new therapeutic target in FOXP3 defect-related cancers." (PMID 26682271, 2015). "The accumulation of FoxP3+Treg cells within lymphocyte clusters surrounding the tumor, as well as abundant B7-H1 expression within this region, have lately also been reported for patients with prostate cancer." (PMID 25365237, 2014). "FOXP3 has been shown to exert its growth inhibitory effect on breast and prostate cancer cells by transcriptionally repressing the expression of specific oncogenes (HER2, SKP2, SATB1 and MYC), and inducing the expression of specific tumor suppressor genes (CDKN1A, LATS2)." (PMID 24406338, 2014). "Similarly, CD4+Foxp3+Treg cells were also higher in prostate cancer bearing mice and glioma tumor bearing mice." (PMID 23587428, 2013). "In breast and prostate cancer, FOXP3 may modulate the expression of oncogenes or tumor suppressor genes, including ERBB2, SKP2, c-Myc, p21 and other important cancer-related genes." (PMID 23888189, 2012). "Men with abundant CD163+ M2 macrophages in prostate tissue have a higher risk of lethal prostate cancer and the interpretation is that the presence of these suppressor cells, CD163+ M2 macrophages, and CD4+ FoxP3+ Tregs may promote an immunosuppressive microenvironment." (PMID 35326519, 2022). "In addition, it was demonstrated that FOXP3 could suppress the proliferation of tumor cells in prostate cancer." (PMID 34670484, 2021). "Finally, somatic inactivating mutations of FOXP3 have been reported in breast and prostate cancers, although notably these findings were not confirmed by recent whole genome sequencing studies of these tumors." (PMID 24406338, 2014). "In addition, FOXP3 was reported as to be a repressor of the oncogene c-MYC in prostate cancer." (PMID 23888189, 2012). "In this study, we have shown that Foxp3+ Tregs infiltrate tumor tissues via the CCL17–CCR4 pathway, and anti-CCR4 treatment exerts an antitumor effect in dogs with advanced prostate cancer." (PMID 35131860, 2022). "Compared with the normal prostate, Foxp3+ Tregs and CCR4+ cells were more frequent in patients with prostate cancer." (PMID 35131860, 2022). "FOXP3+CD25+CD4+ Tregs are known suppressors of CD8+ cytotoxic T cells, and are observed up-regulated in multiple cancer types, including prostate cancer." (PMID 28460462, 2017). "TGFβ is also able to induce Foxp3 expression on CD8+ Tregs, and this subset of suppressor cells contributed to the immunosuppression in certain types of tumor such as prostate cancer." (PMID 24416401, 2014).